CD69 (CD69 molecule)
Diseases named in the same sentence as CD69 in open-access papers (continued):
Sharing a sentence is not in itself a finding about the gene and the disease.
cancer (continued). "Two of the four selected TCRs (TCR1, TCR4) resulted in significant increases in the activation marker CD69 when specifically co-cultured with B2M-transduced, HLA class I-expressing cells but not control or HLA-A2 transduced cancer cells." (PMID 41415427, 2025). "Subsequent assessments of NK cell activation and their capability to effectively target cancer cells revealed significant upregulation of the activation markers CD62L and CD69 on NK cells, signifying their readiness for an immune response and migration into lymphoid tissues." (PMID 40533418, 2025). "However, these cells showed decreased expression of inflammatory markers CD69, FOS and DUSP1 in cancer patients, thus indicating a less active inflammatory profile." (PMID 40340807, 2025). "Interestingly, CD69, CD25, and HLA-DR expression were found to be upregulated after chemotherapy and immunotherapy in cancer patients." (PMID 38339164, 2024). "Similarly, we observed that across multiple cancer types, OTUB2 expression was negatively correlated with the expression of the CTL signature genes GZMB, GZMA and CD69." (PMID 38167274, 2024). "CD8+Trm (CD103+CD49a+CD69+PD-1+CD39+)cells demonstrate enhanced proliferation and cytotoxicity toward autologous cancer cells.Higher density of CD8+Trm in immunotherapy-naive tumors is associated with improved outcomes and Trm density increases during immunotherapy in responders." (PMID 37881432, 2023). "We find that CD69 and SBK1 are differentially expressed in cancer patients who respond to PD-1/PD-L1 blockade when compared with non-responders, and that they are potential biomarkers of response to PD-1/PD-L1 blocking cancer immunotherapy." (PMID 36045683, 2022). "This module included a number of immediate early and growth factor response genes and overlapped with modules previously identified for SDF1 responses in PBs (genes such as CD69 and NR4A2) and growth factor responses in cancer (genes such as EGR1/3, FOS, FOSB, and IER2)." (PMID 36130130, 2022). "CD69 is a type-2 glycoprotein and involved in inflammatory diseases including cancer by interacting with nonspecific legends." (PMID 34633989, 2021). "The results showed that after HLB-apt treatment, T cell activation markers (CD69, CD3E), interleukin (IL-2), and other cytokines in Jurkat cells were significantly overexpressed (P<0.05), indicating an increase in Jurkat cell killing ability against cancer cells." (PMID 40761795, 2025). "Interestingly, the proportion of circulating activated CD69+ T-cells was elevated in cancer patients, which we did not see before the operation." (PMID 37610509, 2023). "However, six weeks after PD, the proportion of peripheral CD3+ lymphocytes expressing the activation marker CD69 was significantly elevated in cancer patients, which we did not see prior to surgery." (PMID 37610509, 2023). "Comparison of lymphocyte differentiation and activation across cancer types revealed cancer-dependent differences for some subsets (e.g., CD25+ T cells, CD137+ T cells or memory B cells), while others showed less variety (e.g., CD69 or effector memory T cells)." (PMID 34135436, 2021). "In the process of module analysis and characteristic molecular screening, we selected two characteristic modules and 10 characteristic molecules (PTPRC, CD2, CD69, IRF8, CCR7, CCL5, il2rb, CXCL10, CCR5, TBX21), which could be used as biomarkers of cancer stem-like cells for GIST patients." (PMID 34925310, 2021). "Moreover, HCQ did not impact the activation of CD8+ T cell in vitro or in vivo, as evaluated by the expression of CD69 and CD137 (markers of the activated CD8+ T-cell), suggesting that the anti-cancer effects induced by HCQ are mediated by CD8+ T cell rather than activating T cells directly." (PMID 30373678, 2018).
cancer (continued). "However, future studies of circulating basophils in cancer may benefit from the inclusion of additional markers for basophil identification (such as CD203c, CD123, and CRTH2), and basophil activation (such as CD203c, CD107a, CD13, CD164, CD69, and histamine or tryptase release)." (PMID 32645919, 2020). "Co-culturing NK cells with pMSCs also inhibited NK cell expression of receptors, including CD69, NKpG2D, CD94, and NKp30, although these co-cultured NK cells were not inhibited in lysing cancer cells in vitro." (PMID 30728068, 2019). "Specifically, in co-cultures with rSFV-infected LNCaP and PANC-1 cells, CD4 and CD8 T cells were found to exhibit a pro-inflammatory profile represented by an increased expression of the activation markers CD69 and CD107 compared to controls with non-infected cancer cells (NT)." (PMID 38425844, 2024).
bacterial infection (10 papers, 2009 to 2022). "Previous studies show that the early T cell activation marker CD69 expresses on stimulated MAIT cells upon bacterial infection; however, CD69 also upregulates in uninfected conditions." (PMID 32582206, 2020). "Few studies are available on CD69 expression by NK cells during in vivo bacterial infections, but up-regulation of this molecule have been shown on NK cells activated in vitro with purified bacterial pathogen-associated molecular patterns (PAMPs)." (PMID 28706510, 2017). "Various viral and bacterial infection models exhibited elevated CD69 expression on T cells." (PMID 35336918, 2022). "However, T cell activation using autologous MoDCs or monocytes is potentially confounded by autoreactivity, as shown with a high CD69 expression of MAIT cells irrelevant to bacterial infection." (PMID 32582206, 2020). "Therefore, the combinatorial marker CD69+CD26++ is able to detect activated MAIT cells dependent on MR1-mediated antigen-presentation from Vα7.2+CD161+ population in bacterial infections." (PMID 32582206, 2020). "Numerous viral and bacterial infection models showed increased CD69 expression on T cells." (PMID 32849474, 2020). "The leading edge genes driving the enrichment of the inflammatory response pathway in response to bacterial infections included several relevant for T‐cell activation (IL1B, CCL5, TNFSF10, GPR183, CD69, SELL), suggesting that cDC2s were undergoing conventional maturation." (PMID 34333764, 2022). "Interpreting our findings in this context, the increased levels of CD69 early after HSCT could be due to the general pro-inflammatory state, as well as due to the recurrent bacterial infections occurring during the first 6 months after transplantation." (PMID 29312341, 2017). "In acute lung injury, as well as in mice studies of intracellular bacterial infection, the evidence points to a role for CD69 as a negative regulator of immune activation." (PMID 24341794, 2013).
inflammation (8 papers, 2017 to 2024). Aberrant reaction of the microcirculation characterized by movement of fluid and leukocytes from the blood into extravascular tissues. "Thus, CD69 was positively correlated to CCL4, indicating that CCL4-mediated eosinophil activation is associated with eosinophilic airway inflammation." (PMID 36555793, 2022). "Current studies have shown that both CXCR6 and CD69 are highly expressed in intestinal resident memory T cells (TRM), which is crucial for the induction of IBD-related chronic inflammation." (PMID 38243324, 2024). "Although we did not see CD69 and CD11a expression in memory CD4 T cells in the allergen challenged lung, we observed that these cells were sufficient to develop airway inflammation without cell recruitment from the circulation." (PMID 28894184, 2017).
immune disorder (5 papers, 2017 to 2025). "CD69 significantly correlates with immune disorders, making it important for prognostic significance." (PMID 36518755, 2022). "The increase in CD69 in patients with MHE would indicate a persistent activation of CD4+ T lymphocytes which may contribute to immune dysfunction, to altered patterns of cytokines and of CD4+ T cells differentiation and facilitate tissue infiltration." (PMID 28751644, 2017). "The T cell immune disorder in DCM is likely due to early immune activation (CD69+ T cell expansion) rather than end-stage exhaustion (no significant increase in PD-1+/CD25+ T cells)." (PMID 40869128, 2025). "Increased CD69 expression in lymphocytes from MCI patients is therefore a marker of several signaling pathways, potentially regulating their activated phenotype and differentiation, resulting in immune dysfunction and altered expression of several cytokines." (PMID 37373554, 2023).
hematologic malignancies (4 papers, 2014 to 2026). "In HD, CD69 was basically expressed by fully mature CD56dimCD16+ cells, whereas in patients with hematological malignancies CD69+ cells were detected in all CD56/CD16 NK cell subsets, independently of their maturation." (PMID 27100180, 2016).
cardiovascular disease (3 papers, 2022 to 2024). "Our results underscore a novel mechanism of PD-1 induction independent of TCR signalling that might contribute to the role of CD69 in the modulation of inflammation and vascular remodelling in cardiovascular diseases." (PMID 35930205, 2022).
neurological disease (3 papers, 2020 to 2025). "Conversely, NK cells and their expression of CD69 or perforin were sparsely detected in brain tissues from control subjects without a history of neurological diseases." (PMID 32870258, 2020).
adenocarcinoma (2 papers, 2015 to 2023). A common cancer characterized by the presence of malignant glandular cells. "Our findings regarding the lymphocyte activation markers CD25 and CD69 in vivo and in stimulated whole blood cultures would support the idea of an impaired immune system in adenocarcinoma patients in a functional context." (PMID 37610509, 2023). "Significantly increased percentages of CD69+/CD94+ NK cells were found in these patients compared to the healthy donors and adenocarcinoma patients." (PMID 26579130, 2015). "The activation marker CD69 appeared to be slightly, but not significantly, elevated on CD3+ T cells of patients with squamous cell (p = 0.81) and adenocarcinoma (p = 0.197) patients compared to healthy controls." (PMID 26579130, 2015).
heart (1 paper, 2021). "Histological observation indicated that the infiltration of T cells in the myocardium of patients with heart transplant rejection show CD69+ activation and perforin activity." (PMID 33732240, 2021).
heart disease (1 paper, 2023). "The results of single-cell RNA-seq analysis collected from heart disease tissue also showed CD69 and chemokine expression." (PMID 36511224, 2023).
hematological cancers (1 paper, 2016). "This was also evident in NK cells from patients with hematological cancers in whom a large part of cells that degranulated were at the beginning CD69- cells." (PMID 27100180, 2016). "This suggested that was CD45RO expression, and not the lost of CD45RA or the gain of CD69, which identified metabolically active, proliferating, NK cells in hematological cancer patients." (PMID 27100180, 2016).
infectious disease (1 paper, 2022). A disorder directly resulting from the presence and activity of a microbial, viral, or parasitic agent in humans. "CD25 + CD4+ T cells are regulatory T cells, Tregs, and cytokines that suppress the immune response and suppress cytokine storms in infectious diseases, so we detected the surface antibody expression of CD25 and CD69." (PMID 35632403, 2022).
respiratory diseases (1 paper, 2014). "We suggest that CD69 could be used as a marker to discriminate between pandemic influenza and other respiratory diseases." (PMID 25254368, 2014).
CD69 also shares sentences with these, for which no sentence is quoted: systemic sclerosis (6 papers); allergic asthma (4); autoimmune myocarditis (3); type 2 diabetes (3); autoimmune uveitis (2); bipolar disorder (2); celiac disease (2); gastrointestinal tumors (2); Graves disease (2); metabolic disease (2); multiple myeloma (2); pulmonary TB (2); Sm (2); streptococcal infection (2); uveitis (2); acute leukemia (1); acute liver failure (1); acute lung injury (1); acute myocardial infarction (1); adenomyosis (1); Airway obstruction (1); alcohol (1); allergic rhinitis (1); Alpha-thalassemia (1); anthrax infection (1); aspergillosis (1); autism (1); B-cell lymphopenia (1); blood cancer (1); brain disease (1).
A further 55 diseases each share a sentence with CD69 in 1 paper.